MORC1 (MORC family CW-type zinc finger 1)
Description:
Required for spermatogenesis (By similarity). Essential for de novo DNA methylation and silencing of transposable elements in the male embryonic germ cells (By similarity).
Synonyms: CT33; MORC; ZCW6
Tractability: PROTAC: ubiquitination databases record sites on it.
Gene: Protein-coding gene on chromosome 3 (108,958,248 to 109,118,134, reverse strand). Ensembl gene ENSG00000114487.
Subcellular location: Nucleus
Gene Ontology:
Molecular function: protein binding; zinc ion binding
Biological process: spermatogenesis; negative regulation of gene expression
Cellular component: nucleus
Genetic constraint (gnomAD): Loss-of-function variants: 37 observed, 85.06 expected, observed/expected ratio (o/e) 0.43, 90% interval 0.33 to 0.57. The upper end of that interval is the gene's LOEUF score, 0.57, which puts it in group 2 of 6, group 1 being the genes least tolerant of losing a copy. Missense variants: 710 observed, 862.32 expected, observed/expected ratio (o/e) 0.82, 90% interval 0.77 to 0.88. Synonymous variants: 297 observed, 304.51 expected, observed/expected ratio (o/e) 0.98, 90% interval 0.89 to 1.07.
Homologues: Orthologues: chimpanzee MORC1 (98% identical), pig MORC1 (79% identical), rabbit MORC1 (70% identical), rat Morc1 (67% identical), mouse Morc1 (65% identical), guinea pig MORC1 (64% identical), dog MORC1 (62% identical), tropical clawed frog morc1 (36% identical), Caenorhabditis elegans morc-1 (20% identical). Paralogues in human: MORC2 (37% identical).
Diseases named in the same sentence as MORC1 in open-access papers:
MORC1 is named in the same sentence as 14 diseases in open-access papers, as found by Europe PMC text mining. Sharing a sentence is not in itself a finding about the gene and the disease. The quoted sentences say what the papers report.
depression (6 papers, 2019 to 2025). "DNA methylation of the MORC1 promoter region is closely associated with depression scale scores and is regarded as a stress-sensitive gene for depression." (PMID 39812044, 2025). "mRNA levels of Morc1, a gene linked to early-life stress and depression, were measured in the medial prefrontal cortex to assess developmental changes." (PMID 39766294, 2024). "Furthermore, they found a link between single-nucleotide polymorphisms in the MORC1 gene and major depression using a genome-wide association study database." (PMID 39766294, 2024). "Moreover, they discovered that certain genetic variants of MORC1 are connected to major depressive disorder (MDD)." (PMID 34331083, 2021). "A multicentric study, eager to identify the role of altered MORC1 methylation patterns in depression and early adversity, analyzed whole-blood DNA methylation in depressed patients and matched healthy controls." (PMID 39766294, 2024). "All these findings reinforce the important role the MORC1 gene plays during development and in the development of depression." (PMID 34331083, 2021). "Recent animal and human studies connected the Morc family CW-type zinc finger 1 (Morc1) gene with early life stress and depression." (PMID 34331083, 2021). "Studies with humans reinforce the link between MORC1 methylation and depression as MORC1 hypermethylation was correlated to signs of depression measured by the Beck Depression Inventory (BDI) in healthy humans." (PMID 34331083, 2021). "This function and its expression in mood-regulating areas already in the early brain development turn Morc1 into a possible candidate gene for mediating early life stress and depression." (PMID 34331083, 2021). "Further studies investigating the neuronal implications of MORC1 in depression are needed to disentangle the potential role of the MORC1 gene." (PMID 34331083, 2021). "Subclinical markers mainly connected to depression, namely Morc1 and GABA, proved to be useful allowing for earlier detection of symptoms of critical postpartum stress." (PMID 33384453, 2020). "Moreover, as there are several markers associated with stress, this study aimed at covering both central and peripheral markers to better characterize Morc1′s possible role in the context of stress and depression and to facilitate translation of obtained results." (PMID 33384453, 2020). "The MORC family CW-type zinc finger 1 (MORC1) gene, has been found to be hypermethylated in buccal cells of individuals who experienced ELA and scored high on the Beck Depression Inventory." (PMID 30984237, 2019). "However, the association between MORC1 methylation and depressive symptoms could be confirmed in all three cohorts highlighting the need for further investigation of the role of Morc1 in ELS and depression." (PMID 34331083, 2021).
Infertility (4 papers, 2014 to 2023). "The finding showed that mutations in MORC1 caused the loss of male-specific germ cells and infertility in mice." (PMID 36980830, 2023). "For a long time, MORC family CW-type zinc finger 1 (Morc1) was only known for its function in mammalian spermatogenesis where its deficiency leads to male-specific germ cell loss and infertility in mice." (PMID 34331083, 2021). "MORC1-deficient mice were previously found to display male-specific germ cell loss and infertility." (PMID 25503965, 2014). "Of interest, some candidates related to sperm and infertility were identified, containing MORC1, TDRD9, ZFYVE21, ADGRB3, SPAG17, CKB, and WDR3, which may have effects on sperm motility and fertilization." (PMID 33477586, 2021).
Anxiety (3 papers, 2019 to 2024). Intense feelings of nervousness, tension, or panic often arise in response to interpersonal stresses. "Finally, we assessed the moderating influence of candidate genes whose level of methylation is associated with the Nr3c1 genotype on anxiety-like behavior: Ank3, Avp, Avpr1a, Avpr1b, Bdnf, Cacna1c, Cyp11b1, Cyp11b2, Fkbp5, Hsd11b1, Igf2, Morc1, Nr3c1, Oxt, Oxtr, Pclo, Slc6a4." (PMID 30655507, 2019). "This study revealed different consequences of stressors during early life on anxiety-like behavior and Morc1 mRNA levels in the mPFC." (PMID 39766294, 2024). "Even though no altered anxiety-like behavior was present in adults, alterations in Morc1 expression were found in adult females with lower expression of Morc1 after MS + social isolation compared to controls and MS." (PMID 39766294, 2024).
mood disorder (2 papers, 2020 to 2021). A cognitive disorder a disturbance in which the person's mood is hypothesized to be the main underlying feature. "Given the role of Morc1 in mood disorders, the mPFC was analyzed regarding Morc1 expression." (PMID 33384453, 2020). "Besides recent human studies investigating MORC1 which significantly increased its connection to mood disorders, its functional role in the brain is still unknown." (PMID 34331083, 2021).
breast carcinoma (1 paper, 2021). "A single nucleotide mutation in MORC1 was first detected in metastatic lobular breast cancer, indicating its potential role in the progression of breast cancer, and a mutation in MORC2 could induce the metastatic progression of triple-negative breast cancer." (PMID 34839357, 2021). "For example, MORC1 is associated with melanoma, lung cancer, and breast cancer." (PMID 34839357, 2021).
colon cancer (1 paper, 2025).
tumor (3 papers, 2021 to 2025). "Additionally, the MORC2 promoter methylation was markedly increased in CRC tissues (P < 0.05), but the methylation of MORC1, MORC3, and MORC4 was significantly lower in the tumor tissues than in negative controls." (PMID 39812044, 2025).
psychiatric disorder (1 paper, 2019). A disorder characterized by behavioral and/or psychological abnormalities, often accompanied by physical symptoms. "We then examined methylation in a shortlist of genes that were previously associated with early life stress and psychiatric disorders as well as placental functioning: Ank3, Avp, Avpr1a, Avpr1b, Bdnf, Cacna1c, Cyp11b1, Cyp11b2, Fkbp5, Hsd11b1, Igf2, Morc1, Nr3c1, Oxt, Oxtr, Pclo, Slc6a4." (PMID 30655507, 2019).
MORC1 also shares sentences with these, for which no sentence is quoted: cancer (5 papers); neurological diseases (2); colorectal cancer (1); cyst (1); malaria (1); Obesity (1).